YY1 (YY1 transcription factor)
Diseases named in the same sentence as YY1 in open-access papers (continued):
Sharing a sentence is not in itself a finding about the gene and the disease.
hepatocellular carcinoma (56 papers, 2009 to 2025). A malignant tumor that arises from hepatocytes. "In hepatocellular carcinoma, the co-expression of the transcription factors YY1 and CP2 was associated with a significantly worse prognosis." (PMID 33315124, 2021). "This study aimed to identify the association of YY1 with HOXD3‐ITGA2 axis in the progression of hepatocellular carcinoma." (PMID 32557953, 2020). "Chromatin immunoprecipitation (ChIP) analysis with a primer set covering the AP1 sites 1 and 2 confirmed the physical association of AP1 and YY1 with the endogenous miR-206 promoter in mouse hepatoma Hepa-1 cells by using specific c-Jun and YY1 antibodies." (PMID 19721712, 2009). "The pleiotropic effects of YY1 in various cancers may also be due to a rewiring of the enhancer–promoter regulatory landscape, as novel enhancer-associated YY1 binding has been implicated in the progression and metastasis of hepatocellular carcinoma 76,77." (PMID 40502787, 2025). "Binding sites in SEs regions were found for Yin-Yang 1 (YY1), another TF associated with cancer progression, hepatocellular carcinoma, high-grade serous ovarian cancer, and triple-negative breast cancer." (PMID 38542080, 2024). "Recent studies have shown that YY1 is also involved in glycometabolism reprogramming, lipid metabolism, and bile acid metabolism in hepatocellular carcinoma (HCC) cells and is strongly related to the development of liver diseases (31, –, 33)." (PMID 38953350, 2024). "The YY1/PcG/DNMT complex via changes in methylation status is important for the development of hepatocellular carcinoma and cervical cancer as well as leukemias such as chronic myeloid leukemia or acute myeloid leukemia." (PMID 35408813, 2022). "Here, we report that 3-hydroxyanthranilic acid (3-HAA) is lower in tumor cells, while adding exogenous 3-HAA induces apoptosis in hepatocellular carcinoma by binding YY1." (PMID 34563230, 2021). "YY1 is a critical component of epigenetic regulatory networks that dictates progression of hepatocellular carcinoma and suppresses the differentiation of hepatocytes." (PMID 34215297, 2021). "In this study, we demonstrate a novel role for YY1 in promoting hepatocellular carcinoma progression by altering HCC cell lipid metabolism independent of oxygen pressure." (PMID 31695789, 2019). "Our previous studies showed that transcription complexes of YY1 promote malignant progression of hepatocellular carcinoma, and patients with high YY1 expression have poor prognosis." (PMID 31799179, 2019). "YY1AP1 is a co-activator of YY1, and activates transcription of stemness regulators in hepatocellular carcinoma." (PMID 31824839, 2019). "In addition, a study on hepatocellular carcinoma has shown that YY1 can form a transcriptional complex with p65 and p300 to activate the quaking (QKI) gene." (PMID 41327312, 2025). "In vitro studies of hepatocellular carcinoma found a positive correlation between YY1 and VEGFA." (PMID 41327312, 2025). "CENPA could also activate downstream CCND1 and NRP2 by binding with the transcription factor YY1, thereby affecting the proliferation and invasion of hepatocellular carcinoma." (PMID 39620895, 2024). "Yin Yang 1(YY1) facilitated hepatocellular carcinoma cell lipid metabolism and tumor progression." (PMID 37858219, 2023). "YY1 reportedly facilitates hepatocellular carcinoma cell (HCC) lipid metabolism and tumor progression by inhibiting PGC-1β-induced fatty acid oxidation." (PMID 38953350, 2024).
hepatocellular carcinoma (continued). "Restoration of C/EBPα in Yin-Yang-1 (YY1) gene expressing hepatocellular carcinoma (HCC) cells induced cellular differentiation and growth inhibition, while knockdown of C/EBPα expression in non-tumor liver cells promoted cell growth." (PMID 24913332, 2014). "Epigenetically, YY1 can recruit HDAC1 to form a repressor complex that downregulates HOXD3 expression, thereby suppressing the ITGA2 pathway in hepatocellular carcinoma cells." (PMID 40940943, 2025). "YY1 overexpression has been shown to promote tumor growth in hepatocellular carcinoma (HCC)." (PMID 41327312, 2025). "Increased expression of YY1 was reported in several cancer types, including prostate cancer, osteosarcoma, breast cancer, glioma and meningioma, gastrointestinal cancer, pancreatic ductal adenocarcinoma, melanoma, and hepatocellular carcinoma (HCC)." (PMID 38339244, 2024). "Hepatitis B virus (HBV), the leading cause of human hepatocellular carcinoma (HCC), could also promote DNAJB4 transcription in HCC cells by upregulating YY1." (PMID 36499297, 2022). "ascertained the MMP1-dependent effect in hepatocellular carcinoma (HCC) progression via interacting with HuR and the metastasis of colorectal cancer via orchestrating the DDX3/YY1/MMP1/PI3K-AKT axis, respectively." (PMID 36483054, 2022). "In accordance with our findings, in hepatocellular carcinoma, survival was decreased in case of combined high protein expression of CP2 and YY1." (PMID 33315124, 2021). "Hence, the precise role of YY1 in hepatocellular carcinoma progression remains unknown." (PMID 32557953, 2020). "This suggests that the overexpression of H2AZ1 in hepatocellular carcinoma may indirectly regulate oxidative stress by targeting TFs such as SIRT1 and YY1." (PMID 38305811, 2024). "YY1 acts as a transcription factor to activate the expression of LOXL1-AS1 and plays a role in regulating the proliferation, apoptosis, and differentiation of hepatocellular carcinoma (HCC) cells." (PMID 39136001, 2024). "USP7 can prevent YY1 from ubiquitin-dependent degradation and stabilizes YY1 expression, which can promote the proliferation, migration, and Epithelial–mesenchymal transformation (EMT) of hepatocellular carcinoma cells (HCCs)." (PMID 39796650, 2024). "Furthermore, co-expression of these two transcription factors, YY1 and LSF, was recently detected in hepatocellular cancers." (PMID 35408813, 2022). "Using the same approach, several cellular transcription factors (CREB, ATF, YY1, STAT1, and STAT2) and chromatin modifying enzymes (PCAF, p300/CBP, HDAC1, SIRT1, and EZH2) have been shown to bind to the cccDNA in human hepatoma cells containing replicating HBV." (PMID 24133502, 2013). "Additionally, in vitro coculture assays revealed that elevated YY1 in hepatoma cells markedly suppressed CD8+ T‐cell activation, whereas YY1 knockdown augmented tumor‐inhibitory capacity, evidenced by increased CD107a surface exposure—a surrogate marker of cytotoxic granule release." (PMID 41322030, 2025). "Using the CIBERSORT deconvolution algorithm on RNA‐seq profiles of primary HCC tumors from the Cancer Genome Atlas Liver Hepatocellular Carcinoma (TCGA‐LIHC) cohort, we found that YY1‐low tumors exhibited a significantly higher proportion of CD8+ cytotoxic T cells than YY1‐high tumors." (PMID 41322030, 2025). "Additional studies found that the transcription factor YY1 (yin yang 1) together with LINC01134, miR-324-5p, and IGF2BP1 (Insulin-like growth factor 2 mRNA binding protein 1), could form a positive feedback loop that mediates the progression of hepatocellular carcinoma." (PMID 37914721, 2023). "Interestingly, the mining of sequencing data of a cohort of patients with liver hepatocellular carcinoma (LIHC) included in The Cancer Genome Atlas (TCGA) shows that YY1, E2F4, and NRF1 expressions were significantly upregulated in the liver of HCC patients." (PMID 37627157, 2023).
prostate carcinoma (55 papers, 2009 to 2025). A carcinoma that arises from epithelial cells of the prostate gland. "Studies reported that YY1 is associated with prostate cancer-specific metabolic profiles, with overexpression of YY1 in prostate tissue and increased mitochondrial energy metabolism activity when normal prostate tissue progresses to cancer." (PMID 40422804, 2025). "Lastly, a study on prostate cancer demonstrated that YY1 is highly expressed in M2-polarized tumor associated macrophages, where it promotes tumor progression by upregulating IL-6 expression." (PMID 41327312, 2025). "YY1 is closely associated with tumor including metastatic breast cancer, colon cancer, gastric cancer, and prostate cancer." (PMID 36798788, 2023). "In fact, YY1 is implicated in prostate cancer development and progression through its regulation of PSA gene expression." (PMID 27340776, 2016). "In vitro, the rs378854-G allele has been associated with reduced binding of the transcription factor YY1, a putative tumor suppressor, and with repressed global transcription in prostate cancer." (PMID 23626673, 2013). "Rs378854 variant reduces binding of the YY1 transcription factor, leading to increased expression of Pvt1 in prostate cancer cell lines while rs6983267 affects binding of the transcription factor TCF4 in CRC cells." (PMID 23240038, 2012). "In particular, we examine a risk locus that is associated with predisposition to prostate cancer and identify a DNA sequence variation that results in a change in the binding site for the nuclear factor YY1 as a potential causative mechanism." (PMID 21814516, 2011). "Interestingly, high expression of YY1 was also associated with a longer DFS in prostate cancer and a better outcome in pancreatic cancer, colon cancer and follicular lymphoma." (PMID 33315124, 2021). "Therefore, we suggest that differential binding of YY1 to the prostate-cancer associated variant rs378854 might be functionally important for the regulation of MYC and/or PVT1 expression." (PMID 21814516, 2011). "YY1 is a multifunctional transcription factor that is upregulated in prostate cancer, colorectal cancer, and other tumors and is closely related to tumor progression." (PMID 40885703, 2025). "YY1 is a well-known oncogenic transcription factor that promotes the initiation, progression, or drug resistance of various cancers, including prostate cancer, cervical cancer, bladder cancer, gastric cancer, and colorectal cancer, through multiple mechanisms." (PMID 40374599, 2025). "Another crosstalk pathway has been elucidated in prostate cancer where YY1 interacts with androgen receptors (AR) to regulate its expression." (PMID 41327312, 2025). "Lowering YY1 expression reduced tumor cell metabolism and promoted apoptosis of prostate cancer cells." (PMID 38339244, 2024). "The purpose of the current study was to determine the mechanism by which YY1 mediates neuroendocrine differentiation of prostate cancer (NEPC) cells undergoing cellular plasticity." (PMID 37771187, 2023). "Preclinical studies in prostate cancer cell lines have demonstrated that downregulating YY1 expression or inhibiting its activity can sensitize tumor cells to the chemotherapy drug cisplatin and enhance its effectiveness." (PMID 37444616, 2023). "The Warburg effect is essential for tumor cells to acquire the energy and metabolize the nutrients that enable synthesis of the macromolecular precursors necessary to support the malignant growth promoted by YY1 in advanced prostate cancer." (PMID 37444616, 2023). "YY1 was shown by Deng and colleagues to interact directly with AR and regulate its transcriptional activity in a concentration-dependent manner in prostate cancer cells." (PMID 37686614, 2023). "Using the Cancer Genome Atlas and Gene Expression Omnibus (GEO) databases, we bioinformatically analyzed YY1 expression in prostate cancer (PCa)." (PMID 37771187, 2023).
prostate carcinoma (continued). "Current researches have found that YY1 performs a cancer-promoting effect in breast, colon, stomach, and prostate cancer." (PMID 35791393, 2022). "YY1 has been shown to inhibit tumor suppressor and thus promote the proliferation of prostate cancer cells." (PMID 35359580, 2022). "Regulates by androgen; interacts with YY1 to co-activate downstream oncogenic genes; promotes prostate cancer cell growth." (PMID 35547880, 2022). "Further study of the mechanism found that SNHG14 directly binds to miR-5590-3p, while the 3’UTR of miR-5590-3p can interact with YY1 protein in prostate cancer." (PMID 36626426, 2022). "From candidates identified, YY1 was selected for further analysis as it has previously been shown to negatively regulate DR5 expression in prostate cancer." (PMID 34597666, 2021). "YY1 is highly expressed in many types of cancerous tissues, including prostate cancer, colon cancer, liver cancer, and lung cancer." (PMID 32042322, 2020). "YY1 inhibits XAF1 expression in prostate cancer cells lines through HDAC1 dependent mechanism and thereby induces cancer progression." (PMID 31824839, 2019). "There are multiple reports which unequivocally show upregulation of YY1 in several prostate cancer cell lines as well as prostatic neoplasia of patients." (PMID 31217904, 2019). "Similar to other cancers, YY1 has been reported to be overexpressed in prostate cancer also and has been suggested to play essential role in proliferation, invasion, metastasis and drug resistance." (PMID 31824839, 2019). "Mechanistically, to promote prostate cancer growth, YY1 has been shown to repress the expression of X-linked inhibitor of apoptosis (XIAP) associated factor-1 (XAF1), a tumor suppressor in prostate cancer cells." (PMID 31824839, 2019). "Further, YY1 also contributes to the metastatic potential of the prostate cancer cells by mediating transcriptional repression of heterogeneous nuclear ribonucleoprotein M (hnRNPM), which is an inhibitor of migration and invasion of prostate cancer cells." (PMID 31824839, 2019). "The mammalian PcG protein SFMBT2 has been shown to play an important role in prostate cancer cell growth through HOXB13 gene regulation via interaction with YY1." (PMID 27340776, 2016). "In conclusion, our study provides evidence that SFMBT2 regulates prostate cancer metastasis either by direct repression of YY1 target genes such as MMP-9, MMP-26, and N-CoR and by indirect regulation of MMP-2, MMP-3, and KAI1 gene expression." (PMID 27340776, 2016). "YY1 is overexpressed in many types of cancer, including metastatic breast cancer, colon cancer, gastric cancer and prostate cancer." (PMID 27225481, 2016). "In prostate cancer, YY1 has two binding sites within the prostate stem cell antigen (PSCA) promoter facilitating development of malignant human prostate cancer." (PMID 24674326, 2014). "This mini review summarizes the current reported studies and Bioinformatic analyses on the role of YY1 in the pathogenesis of prostate cancer." (PMID 25053986, 2014). "Some datasets demonstrated overexpression of YY1, others demonstrated similar expression levels as normal prostate controls, and a few demonstrated decrease in YY1 in prostate cancer compared to normal prostate epithelium." (PMID 25053986, 2014). "In prostate cancer, YY1 physically interacts with androgen receptor (AR), which is required for the optimal transcriptional activity of AR in promoting the transcription of the prostate-specific antigen (PSA), a protein enhancing cell migration and metastasis." (PMID 24674326, 2014). "Studies by us and others have examined the role of YY1 in the regulation of EMT in human prostate cancer cell lines." (PMID 25053986, 2014). "Death receptor 5 (DR5) has been implicated in the prognosis of several cancers and it has been previously shown that it is negatively regulated by Yin Yang 1 (YY1) in prostate cancer cell lines." (PMID 25174820, 2014).
prostate carcinoma (continued). "Our laboratory has examined a gene product, namely, YY1, that is overexpressed in many cancers including prostate cancer." (PMID 25053986, 2014). "This review has briefly discussed the role of YY1 in the pathogenesis of prostate cancer as a model." (PMID 25053986, 2014). "We will present studies on the role of YY1 in the pathogenesis of prostate cancer, its role in resistance, and findings on YY1 gene analysis in bioinformatics datasets." (PMID 25053986, 2014). "YY1 also participates in the repression of HOXB13 expression in prostate cancer cells through an epigenetic mechanism involving histone acetylation modification." (PMID 24705708, 2014). "Although the function of YY1 in prostate cancer is not fully known, it was reported recently that YY1 forms a complex with AR, which together binds to the ARE within the PSA promoter, stimulating gene expression." (PMID 22536409, 2012). "With respect to clinical prognosis, it is interesting to note that lower expression of nuclear YY1 correlates with a poorer outcome for prostate cancer, with the data suggesting that decreased YY1 levels give metastatic cells a survival advantage." (PMID 21814516, 2011). "YY1 is a pleiotropic transcription factor expressed in prostate glandular epithelium and basal cells, and its expression is positively correlated with prostate cancer metastasis." (PMID 20500816, 2010). "However, pyripyropene O is a natural marine product that can bind directly to the transcription factor YY1 and induce apoptosis in prostate cancer cells by targeting the YY1/DR5 axis." (PMID 40422804, 2025). "This experimental result indicates that PyrO binds to YY1 protein in prostate cancer cells." (PMID 40422804, 2025). "In addition, it has been proposed that the YY1 complex in M2 macrophages promotes prostate cancer progression by upregulating IL-6." (PMID 40422804, 2025). "YY1 promotes the secretion of exosomes to promote prostate cancer progression, and YY1 upregulates polycom, also named pentraxin domain containing 1 (SVEP1), in cancer-associated fibroblasts (CAFs), which secrete miR-146a-5p and increase urothelial bladder cancer resistance." (PMID 40867514, 2025). "In addition, we showed that pyripyropene O induces apoptosis in prostate cancer cells by targeting the YY1/DR5 axis." (PMID 40422804, 2025). "Targeting the YY1/DR5 axis against prostate cancer is a novel strategy." (PMID 40422804, 2025). "Moreover, YY1 mRNA stabilization induced by HnRNP L can promote the transcription of PD-L1 in prostate cancer cell lines." (PMID 38347631, 2024). "A recent study applied H3K27ac-ChIP-seq in M2 macrophages and THP-1 cells and revealed that M2-specific enhancers were enriched in Yin Yang, 2 zinc finger nuclear transcription factor (YY1) signals, while YY1 increased macrophage-induced prostate cancer progression by upregulating IL-6." (PMID 39516356, 2024). "Many types of cancer-related cells, including B-cell lymphoid tumors, follicular lymphomas, acute myeloid leukemia, gastric cancer, osteosarcoma, cervical cancer, brain tumors, prostate cancer, colon cancer, ovarian cancer, breast cancer, and lung cancer cells, exhibit a high expression of YY1." (PMID 38347631, 2024). "The proposed mechanism provides a possible explanation for YY1 malfunction in prostate cancer." (PMID 37686614, 2023). "While YY1 acts as a tumor suppressor in pancreatic cancer, it exhibits a tumor promoting function in colon cancer and prostate cancer." (PMID 33315124, 2021). "Through proteomic analysis, YY1 was acknowledged as a regulator in prostate cancer." (PMID 32943988, 2020). "YY1 is upregulated in human prostate cancer cell lines and tissues." (PMID 31694235, 2019). "In addition to repression of regular genes, YY1 has also been shown to repress tumor suppressive miR-146a in prostate cancer cells upon interacting with EZH2 and thereby promotes prostate tumor growth." (PMID 31824839, 2019).